MGMT (O-6-methylguanine-DNA methyltransferase)
Diseases named in the same sentence as MGMT in open-access papers (continued):
Sharing a sentence is not in itself a finding about the gene and the disease.
tumor (continued). "Second, the outcome of the disease may depend on the histopathological classification and molecular characteristics of the tumor, in particular O6-Methylguanine-DNA Methyltransferase (MGMT) methylation status." (PMID 40640872, 2025). "The biological reasons for these observations are as yet unclear, although molecular characterization reveals that females are more likely to have MGMT methylated disease, secondary GBMs, differences in tumor location, and molecular and metabolic mechanistic triggers." (PMID 40362575, 2025). "Importantly, tumor-specific variability in methylation thresholds and expression patterns underscores the need for cancer-type-tailored strategies when leveraging MGMT as a biomarker." (PMID 40895460, 2025). "The efficacy of this chemotherapeutic protocol depends on the methylation status of the O6-methylguanine-DNA methyltransferase (MGMT) gene promoter, where high methylation levels are associated with increased tumor cell sensitivity to radio- and chemo-induced mutagenesis." (PMID 40775789, 2025). "MGMT methylation is another key factor influencing tumor behavior." (PMID 40261557, 2025). "However, its efficacy is severely reduced when tumour cells express the MGMT protein, and this limitation applies to other cancer types also." (PMID 40377133, 2025). "Notably, the MGMT methylation status outperforms conventional prognostic indicators such as tumor grade, performance status, and patient age in predicting therapeutic response, underscoring its clinical relevance." (PMID 40628732, 2025). "Including molecular biomarkers beyond MGMT, like IDH1/2 mutation status, ATRX loss, TERT promoter mutation, EGFR amplification, and 1p/19q co-deletion, can improve the model’s understanding of tumor biology." (PMID 41584616, 2025). "MGMT methylation correlates with distinct imaging features, including tumor location and necrosis." (PMID 41584616, 2025). "Patient #1, in whom additional meldonium intake arrested tumor growth, had a methylated MGMT." (PMID 40295665, 2025). "In contrast to MGMT analysis, promising results were achieved for the prediction of IDH mutation status, demonstrating the potential of imaging data as a non-invasive measurement for tumor stratification purposes." (PMID 41561752, 2025). "This methodological decision aligns with recent findings that the proportion of non-enhancing tumor is associated with MGMT promoter methylation." (PMID 41247617, 2025). "Molecular testing of a tumor after surgery for MGMT expression could be helpful for identifying potential responders to TMZ." (PMID 40806825, 2025). "GBM is a highly aggressive tumor with a poor prognosis, and reductions in tumor size may be influenced by multiple factors, including the effects of chemoradiotherapy, the patient’s MGMT methylation status, and other biological variables." (PMID 40224189, 2025). "This is further complicated by the heterogeneous expression of MGMT within the tumor, as each subpopulation within the tumor may create distinct unique microenvironment due to different levels of immune cell recruitment." (PMID 41476598, 2025). "This prompted the development of numerous strategies to reduce tumor MGMT content." (PMID 39997039, 2025). "Previous studies suggest that MGMT status may modulate and impact the local immune response to the tumor." (PMID 41476598, 2025). "Here we used cell culture and an orthotopic human xenograft mouse model to investigate whether MGMT KO affected cellular proliferation, clonogenicity in soft agar and tumor growth in vivo." (PMID 40336841, 2025). "In moderately diffuse tumors with methylated MGMT, the combination of reduced residual tumor burden after resection and increased chemosensitivity may synergistically contribute to the observed improvements in PFS and OS." (PMID 40149329, 2025).
tumor (continued). "The total tumor/edema ratio was significantly lower in MGMT methylated group from both DeepBraTumIA (0.338, Std 0.045) and Raidionics (0.335, Std 0.052) segmentations compared to non MGMT methylated [DeepBraTumIA (0.891, Std 0.225) and Raidionics (0.770, Std 0.125)]." (PMID 41476598, 2025). "The β‐Catenin‐MGMT functional axis has been ubiquitously reported, but the factors that control the β‐Catenin‐MGMT signaling cascade in this rare tumor are still unknown." (PMID 39041891, 2024). "Thus, reduced transcription of the MGMT gene due to hypermethylation leads to increased tumor sensitivity to TMZ." (PMID 38510602, 2024). "Risk factors for survival identified herein were age, tumor size, and lack of MGMT promoter methylation." (PMID 39545524, 2024). "Furthermore, given the primary objective of a predictive biomarker is forecast treatment response, our results suggest that MGMT methylation in tumor approaches statistical significance in predicting survival although our limited sample size." (PMID 38762534, 2024). "Specifically, patient ID2 was diagnosed with MGMT methylated GB and underwent tumor resection." (PMID 38762534, 2024). "MGMT promoter methylation was found in nine cases (10%) across tumor locations: five cases in the thalamus (11%), one case in the brainstem (4%), one case in the spinal cord, and two cases in other locations (20%), but there was no statistical difference (p = 0.304)." (PMID 39061104, 2024). "The impact of MGMT promoter methylation on tumor perfusion is debated." (PMID 39036439, 2024). "As shown in the public cohorts, MGMT‐silenced cases had a trend toward longer OS (71.3 vs. 28.1 months, p = 0.208), which resulted significant in a multivariable analysis including patients' and tumor characteristics." (PMID 39618336, 2024). "Preclinical data suggests that in MGMT-silenced tumors, this could improve tumor cell death 147-149." (PMID 38817857, 2024). "Kaplan–Meier curves were obtained and the survival analysis was fitted into a Cox proportional hazard model with the data variables of age, sex, presence of other cancer, number of surgical resections, tumor location, bevacizumab treatment, and MGMT promoter methylation status." (PMID 39684714, 2024). "Patients' and tumor characteristics according to MGMT status in the INT cohort." (PMID 39618336, 2024). "Patients who have experienced a relapse a few months after the completion of adjuvant temozolomide treatment and whose tumours contain a methylated MGMT promoter may be the most suitable candidates for rechallenge with temozolomide." (PMID 39099691, 2024). "Thus, methylation-specific PCR (MCP) is frequently used to detect the methylation status within the MGMT promoter, stratifying patients’ tumor samples into MGMT methylated and unmethylated." (PMID 38811596, 2024). "Furthermore, Hispanic ethnicity was found to predict time to recurrence independent of established clinical prognostic factors, including age at diagnosis, baseline functional status, tumor MGMT methylation, and treatments received." (PMID 38672661, 2024). "Mechanisms of TMZ resistance are multifactorial and encompass both tumor-intrinsic factors, such as MGMT expression and DNA repair capacity, and tumor microenvironment-mediated processes, including hypoxia-induced signaling pathways and immune evasion mechanisms." (PMID 39057168, 2024). "The phase II/III trial NRG-BN007 (NCT04396860) compared the usual treatment of RT and temozolomide to RT in combination with IT (ipilimumab and nivolumab) for treating patients with newly diagnosed unmethylated MGMT (tumor O-6-methylguanine DNA methyltransferase) GBM." (PMID 38893165, 2024). "This is reflected when analyzing how an increase in survival was observed (HR: 0.51, 95%, CI: 0.31–0.84) in patients whose tumor had the MGMT gene promoter methylated, and who received radiotherapy and temozolomide, compared to those who received radiotherapy only." (PMID 39767683, 2024).
tumor (continued). "In this study, we reported for the first time the biological importance of MGMT and a new mechanism by which MGMT expression is regulated by MEN1, that is, the loss of MEN1controlled MGMT transcription and tumor chemosensitivity to TMZ via the activation of β‐Catenin." (PMID 39041891, 2024). "MGMT inhibitors control MGMT expression and activity in the tumor." (PMID 38811596, 2024). "To investigate whether MGMT methylation status had predictive value in tumor-bearing patients, we conducted a small-scale epidemiologic study using clinical data from the ARETHUSA trial." (PMID 39594133, 2024). "Patients' and tumor characteristics according to MGMT methylation status in the public cohorts." (PMID 39618336, 2024). "Tumor progression was also negatively correlated with MGMT methylation (β = −33.7, p < 0.0001)." (PMID 38893250, 2024). "Tumor was extensively necrotic and MGMT testing was inconclusive due to extensive necrosis." (PMID 38340693, 2024). "Additionally, tumor grade and MGMT expression were found to be independent factors affecting progression‐free survival (PFS)." (PMID 39118481, 2024). "GBM is also an inherently heterogeneous tumor and one study looked at changes in MGMT promoter methylation status, dividing the study into three groups: methylated, unmethylated, and methylated to unmethylated, and observed that methylation status changed in recurrent GBMs after standard treatment." (PMID 39195222, 2024). "The NRG BN007 phase 2/3 trial evaluated the combination of nivolumab and ipilimumab using the better-tolerated dosing regimen explored in CHECKMATE 143 and allowing the use of tumor-treating fields at the treating physicians’ discretion in newly diagnosed MGMT promoter unmethylated GBM." (PMID 39766048, 2024). "These prognostic factors can be listed as: age, Karnofsky Performance Score (KPS), recurrence interval, tumor volume, surgery before reirradiation, concurrent systemic therapy, reirradiation dose, and O6-methylguanine-DNA methyltransferase (MGMT) gene promoter methylation status." (PMID 38383875, 2024). "Among the tumor tissue samples, 51/89 (57.3%) showed MGMT promoter methylation.The specificity of the detection in the CSF and serum samples reached 100%.The sensitivity of MGMT promoter methylation detection in CSF and serum was 26/40 (65.0%) and 19/51 (37.3%), respectively (p < 0.05)." (PMID 39063215, 2024). "Key biomarkers such as MGMT promoter methylation, IDH1/2 mutations, EGFR amplification, and TERT promoter mutations, etc., are examined for their roles in prognosis, therapeutic response, and tumor classification." (PMID 39767571, 2024). "However, the therapeutic efficacy of these drugs is often undermined by the active presence of MGMT within the tumor cells, which effectively repairs the very DNA damage these chemotherapeutic agents are designed to inflict." (PMID 39055560, 2024). "Investigations are underway for alternatives to temozolomide in MGMT-unmethylated tumour patients." (PMID 39099691, 2024). "The MGMT promoter in the initial tumor specimen was methylated in 21 (52.5%) cases." (PMID 39335591, 2024). "One could even argue the case for replacing TMZ with FK866 in MGMT+ tumours, which are significantly less likely to respond to TMZ or other alkylating agents used in recurrent GBM, including lomustine." (PMID 38893173, 2024). "Radiotherapy was omitted due to age in conjunction with a methylated MGMT promotor in this tumor." (PMID 39340558, 2024). "MGMT inhibitors could be delivered accumulatively to local tumor tissues, but minimally to healthy tissues." (PMID 39055560, 2024). "Younger, fit patients with MGMT-methylated tumours may benefit from temozolomide and lomustine combined with radiation therapy, but efficacy is inconclusive and toxicity may be higher." (PMID 39099691, 2024). "Patients with MGMT-unmethylated tumours may benefit from clinical trials due to their poor prognosis and response to standard treatments." (PMID 39099691, 2024).
tumor (continued). "DSC-derived normalized cerebral blood flow/volume (nCBF/nCBV) and ASL-derived nCBF in tumor and perifocal edema were analyzed in patients with available IDH-mutation (n = 67), pTERT-mutation (n = 39), 1p/19q codeletion (n = 33), and MGMT promoter methylation (n = 31) status." (PMID 39036439, 2024). "However, MGMT status is captured on tumor tissue which, given the difficulty in acquisition, limits the use of this molecular feature for treatment monitoring." (PMID 38612892, 2024). "Although DL models have been developed to predict MGMT promotor methylation, achieving remarkable success, further radiogenomic models should be created to predict methylation status of other segments of tumour DNA." (PMID 39009914, 2024). "In high-grade tumors, treatment usually consists of maximal resection of the tumor (if feasible) followed by chemotherapy and radiotherapy depending on tumor grade and analysis of molecular markers (i.e., 1p/19q codeletion, IDH mutation, and MGMT promoter methylation)." (PMID 39338390, 2024). "Patients ID1, ID2, ID28, ID32 and ID34 had an MGMT methylated tumor." (PMID 38762534, 2024). "Similarly, SEPTIN9 participates in cytokinesis during the cell cycle, while SHOX2 is a transcription factor involved in proliferation, migration and colony formation and MGMT inhibits tumour formation." (PMID 38903861, 2024). "Patient ID34 underwent complete resection of a methylated MGMT tumor." (PMID 38762534, 2024). "Consequently, tumours with an unmethylated MGMT promoter and with corresponding high MGMT RNA expression (MGMT positive) are generally insensitive to TMZ44." (PMID 39572533, 2024). "Thus, the MGMT status offers insights into the anticipated tumor responses to chemotherapy and guides oncologists in tailoring GBM treatment." (PMID 39123366, 2024). "In 2018, another study employed similar inputs including patient age, sex, Karnofsky Performance Status, MGMT methylation, and subventricular zone tumor location classification through a Radiation Therapy Oncology Group nomogram to achieve a c-index of 0.70 at 12 months survival." (PMID 38798600, 2024). "Patients ID2 and ID32 also carried an MGMT methylated tumor sample." (PMID 38762534, 2024). "In addition, transgenic mice overexpressing MGMT in their skin are protected against tumor formation upon exposure to MNU and nimustine (ACNU)." (PMID 36902118, 2023). "This was in concordance with an unmethylated MGMT-promoter of the tumor." (PMID 38136371, 2023). "In addition, the magnitude of effect of the MGMT methylation status in the EoR was increased when adjusting for preoperative tumour volume." (PMID 37373988, 2023). "Furthermore, we aim to enable accurate payload delivery by leveraging AuNPs as nanocarriers for temozolomide and MGMT inhibitors directly to the tumor site, potentially reducing chemotherapy resistance and systemic side effects." (PMID 37531222, 2023). "This study aims to evaluate whether the radiomic features extracted from multiple tumor subregions using multiparametric MRI can predict MGMT promoter methylation status in GB patients." (PMID 38203308, 2023). "When the MGMT gene locus become methylated (i.e., hypermethylated), the amount of DNA repair across the genome reduces, leading to increased sensitivity to cytotoxic medications, making the tumor more responsive to chemotherapy." (PMID 36831683, 2023). "Our results suggested that there may be some interaction between the aggressiveness of the tumor and MGMT expression." (PMID 36831707, 2023). "MGMT methylation gradually increased in parallel with tumor progression and may serve as a biomarker for assessing CRC progression." (PMID 37510370, 2023). "NF2, FAM3B, and MGMT are primarily involved in regulating the tumor immune microenvironment." (PMID 37264476, 2023). "Tumor molecular markers as IDH1 mutation and MGMT methylation status may provide future treatment targets." (PMID 37071297, 2023).
tumor (continued). "Given that the systemic delivery of MGMT inactivators exacerbates collateral toxicities, the synthesis of tumor-targeting inactivating agents might be expected to circumvent this." (PMID 37631385, 2023). "Here, we have studied the methylation status of the MGMT promoter in histological tumor samples obtained from patients with LMS treated with dacarbazine, aiming to ameliorate dacarbazine use in these STS and to find out if the methylation of MGMT correlates with clinical response." (PMID 37371106, 2023). "Interestingly, the Chekenay group used Bortezomib pretreatment with TMZ, to increase the MGMT-methylation within tumor tissue." (PMID 36768201, 2023). "The impact of MGMT methylation on surgical resection of tumours, however, remains unexplored." (PMID 37373988, 2023). "However, when tumor factors were considered, the diameter of the tumor in the MGMT-positive group was 22.9 mm." (PMID 37161026, 2023). "In contrast to other studies, we could not find a correlation between the ADC values or the normalized ADC values and the MGMT methylation status in the enhancing tumor parts." (PMID 36900177, 2023). "Data from this study support testing of tumour MGMT promoter methylation in patients with dSDH wtGIST to identify those patients who may benefit from most from TMZ therapy." (PMID 36198483, 2023). "However, in our study, a subgroup of patients with a low MGMT protein expression and MGMT promoter methylation demonstrated a benefit in median OS compared to patients expressing the MGMT protein in tumor cells." (PMID 37047153, 2023). "Moreover, one patient, with an IDH1 wild-type and MGMT unmethylated tumor received a total of six doses of pembrolizumab with overall stable disease." (PMID 37188783, 2023). "In contrast to other studies, we could not find a correlation between the ADC values or the normalized ADC values and the MGMT methylation status in the enhancing tumor." (PMID 36900177, 2023). "However, MGMT can repair such DNA damage, affecting the sensitivity of tumor cells to alkylating agents such as carmustine (BCNU), temozolomide and streptozotocin." (PMID 37026932, 2023). "Additionally, patients with a methylated Methylguanine methyltransferase (MGMT) promoter in tumor samples present a better prognosis and higher temozolomide sensitivity due to MGMT enzyme inactivation." (PMID 36765718, 2023). "Wild-type DNA-repair-proficient mice showed a non-linear tumor formation, whereas MGMT-deficient mice developed tumors in a linear, dose-dependent manner." (PMID 36902118, 2023). "A higher MGMT methylation percentage was related to lower preoperative tumour volume (coef." (PMID 37373988, 2023). "However, tumor cells can develop temozolomide resistance via DNA damage repair systems such as the O6-methylguanine-DNA methyltransferase (MGMT) repair mechanism and the DNA mismatch repair (MMR) system." (PMID 37723574, 2023). "In 7 cases, MGMT promoter methylation in the tumour was lost in culture (M→UM, 11%)." (PMID 37620410, 2023). "Functional MGMT blocks the tumor cell death mediated by alkylating drugs such as TMZ." (PMID 37047153, 2023). "miR-198 is a tumour suppressor miRNA that promotes TMZ sensitivity in GBM by downregulating MGMT." (PMID 37891744, 2023). "In addition to methylated and carboxymethylated ASPs, a numberof other ASPs were detected at varying frequencies following incubationof MGMT with paired colorectal normal and tumor DNA samples." (PMID 37983188, 2023). "The elevated tumor mutational burden of 15 mutations/megabase, may suggest these tumors have increased levels of tumor neoantigens and therefore more immunogenic, which could be due to impaired DNA repair in the setting of MGMT promoter hypermethylation." (PMID 37387791, 2023).